ALB (albumin)
Diseases named in the same sentence as ALB in open-access papers (continued):
Sharing a sentence is not in itself a finding about the gene and the disease.
colitis (continued). "The accumulation of albumin-encapsulated liposomes in an inflammatory site in the coon using a mice model of colitis has also been evaluated." (PMID 33810483, 2021). "Several studies have reported on the therapeutic efficacy of drug-loaded albumin-encapsulated liposomes for the treatment of various types of solid cancers and colitis." (PMID 33810483, 2021). "In the present study, we confirmed that HYJJ considerably alleviated of DSS-induced colitis, as evidenced by the improved intestinal injury and fecal albumin, as well as feces blood." (PMID 34122086, 2021). "Among DSS-treated mice, the mean albumin level was significantly lower among the D++, compared to the D+ (p < 0.05) and D− (p < 0.05) group, consistent with a worse colitis seen in the D++ group." (PMID 30065252, 2018). "Consistently, pea seed albumin extract ameliorated DSS-induced colitis in mice by reducing the expression of inflammatory markers in colonic tissues." (PMID 28524086, 2017). "In addition, Vangl2ΔM/ΔM colitis mice exhibited lower levels of serum albumin and higher levels of fecal α1-antitrypsin than WT mice." (PMID 39899477, 2025). "TNF-α–siRNA and gallic acid – mediated graphene quantum dots (GAGQDs) encapsulated in bovine serum albumin nanoparticles were demonstrated to effectively treat colitis, maintain bacterial gut microbiota homeostasis, and modulate mood and cognitive dysfunctions in mice." (PMID 38024319, 2023). "In addition, low ALB levels at diagnosis of UC can predict the occurrence of acute severe colitis in the future." (PMID 36895716, 2023). "Furthermore, the albumin extracts from pea seeds showed anti-inflammatory effects in DSS-induced colitis in C57BL/6J male mice." (PMID 37444265, 2023). "Similarly, the permeability of Evans Blue-binding albumin (molecular weight 69 kDa) into the brain parenchyma of mice with acute DSS-induced colitis was increased or unchanged, respectively." (PMID 36232412, 2022). "The protective effects of pea albumin against DSS-induced colitis may be attributed to the anti-inflammatory effects of BBIs within the large intestine." (PMID 36079868, 2022). "In this regard, we hypothesized that pea albumin oral administration could have a positive effect on colitis alleviation." (PMID 36079868, 2022). "•Modified albumin ameliorated DSS colitis and improved systemic redox state." (PMID 33601276, 2021). "•Albumin, the major thiol antioxidant in body, is decreased and oxidized in colitis." (PMID 33601276, 2021). "Therefore, above data suggest that PIC/CAPE-loaded albumin NP improves the overall morphology of the colon during active colitis in a murine model of DSS-induced colitis." (PMID 30430451, 2019). "At day 7, the mean serum albumin was less in all groups with colitis than corresponding controls." (PMID 30065252, 2018). "Additionally, albumin is known to aggregate at sites of inflammation and tumour due to its affinity towards neutrophils, hence albumin nanoparticles could be used to target inflamed colon tissue in colitis." (PMID 30430451, 2019). "In the acute experimental colitis mice, the relative cecum weights and serum biochemical parameters, including AST, ALT, CPK, LDH, total protein, and albumin were significantly changed." (PMID 35159523, 2022). "In the present study, we have tested albumin-loaded nanoparticles containing PIC and CAPE for the first time in a DDS-induced murine model of colitis." (PMID 30430451, 2019). "Dextran sulphate sodium was used to induce colitis in mice and effect of either free CAPE/PIC or CAPE/PIC loaded albumin nanoparticles treatment was observed on disease development and levels of cellular p65 and HIF-1α." (PMID 30430451, 2019). "This study aimed to evaluate the abilities of two peptides derived from egg albumin transferrin, IRW and IQW, to treat enteritis in a mouse model of Citrobacter rodentium-induced colitis by evaluating serum metabolomics and gut microbes." (PMID 31001226, 2019).
colitis (continued). "In DSS-induced colitis, Westernized HFD-feeding enhanced neutrophil infiltration as indicated by enhanced myeloperoxidase activity, and pea seed albumin extracts reduced inflammatory cell infiltration into the colon." (PMID 28524086, 2017). "Serum levels of ALT, AST, and ALB, as markers that assess liver injury, were also found to be abnormal in DSS-induced colitis mice, further supporting that the liver injury is the extra-intestinal manifestation of colitis." (PMID 34603071, 2021). "PIC-loaded albumin NP (picture 4) and CAPE-loaded albumin NP (picture 4) shows no sign of blood clots during experimental colitis." (PMID 30430451, 2019). "Hence, in the present work, we have evaluated the effect of albumin NP loaded with PIC and CAPE at 20 mg kg−1 day−1 in a mouse (C57BL/6) model of DSS-induced colitis." (PMID 30430451, 2019). "Thus, after careful optimisation, we selected 20-mg drug concentration to formulate albumin NP loaded with PIC and CAPE for evaluation of the anti-inflammatory potential of PIC and CAPE in chemically induced mouse model of colitis." (PMID 30430451, 2019). "Of particular interest, our results found that pea albumin significantly alleviated the upregulation of phosphorylation of NF-κB and STAT3, indicating that pea albumin contains bioactive compounds with the ability to block the NF-κB and STAT3 signaling pathways in DSS-induced colitis." (PMID 36079868, 2022). "However, no studies have yet explored the potential efficacy of albumin in the treatment of colitis." (PMID 36590401, 2022). "The discordance between the CRP and albumin and the UCEIS score within the subset of patients who underwent sigmoidoscopy further supports the finding that traditional biochemical markers used in idiopathic IBD are of limited use in the assessment of irAE colitis." (PMID 32418993, 2020). "The methylation level of RUNX3 P2 did not correlate with age, sex, nutritional status, CRP, albumin, PUCAI, or the extent of colitis (Paris E1–E4)." (PMID 36140736, 2022). "There have been no previous published reports of albumin NP, loaded with PIC and CAPE, being evaluated in a murine model of chemically induced colitis." (PMID 30430451, 2019). "However, these factors are not specific to ICI-induced colitis, and moreover, it has been reported that the biochemical parameters, including CRP, albumin, and hemoglobin, did not correlate with the severity of ICI-induced colitis." (PMID 38461170, 2024). "Collectively, our results demonstrate the establishment of both acute and chronic colitis models in NHP and show that MRI with a reversible albumin-bound blood pool contrast agent may be a useful, noninvasive method to localize and monitor colitis." (PMID 26282376, 2015).
edema (39 papers, 2008 to 2026). An abnormal accumulation of fluid beneath the skin, or in one or more cavities of the body. "Reduced serum albumin levels predispose patients to brain edema, thereby leading to impaired consciousness and SAE." (PMID 39135753, 2024). "Serum albumin concentration was negatively associated with the presence of oedema (aOR = 0.75 [95% CI: 0.71, 0.78] per g/L, p<0.001)." (PMID 35398787, 2022). "Cav-1 is an integral protein for caveolae formation, with upregulation associated with enhanced albumin extravasation and the development of vasogenic cerebral edema." (PMID 31333402, 2019). "Systematic reviews: Four previous reviews were identified that addressed the use of albumin in patients with oedema or hypalbuminaemia." (PMID 41281089, 2025). "From a clinical perspective, there was a correlation between Edema/Serous effusion and a reduction in ALB levels." (PMID 39263576, 2024). "Conversely, there were more subjects in the albumin arm who presented with pulmonary edema and/or pulmonary infections." (PMID 37509478, 2023). "More adverse events (mild-to-moderate pulmonary edema and symptomatic intracranial haemorrhage) were reported in the Albumin-treated patients." (PMID 34666786, 2021). "The instrument enabling evaluation of pressure ulcer risk takes into account the following factors: condition of the cardiovascular system, serum albumin level, application of mechanical ventilation and presence of oedema." (PMID 33669609, 2021). "The stembark of L. sericeus was evaluated for anti-inflammatory properties using egg albumin and xylene-induced oedema models." (PMID 33299815, 2020). "The increase in MMP-9 produced by albumin further implicates both astrocytes and albumin in the acute and long-term complications of acute CNS insults, including cerebral edema and epilepsy." (PMID 22507553, 2012). "Decreased cerebral edema after hyperoncotic albumin administration was shown in one included randomized trial." (PMID 18318896, 2008). "Across the mapped studies, researchers variably measured weight loss, urine volume, serum albumin levels, fractional excretion of sodium, time to oedema resolution or plasma volume expansion, without consistent timing, units or definitions." (PMID 41281089, 2025). "Donor fetuses, due to the transfusion of albumin in addition to Hb, may suffer decreased oncotic pressure, potentially leading to fetal hydrops." (PMID 39337856, 2024). "However, adverse events related to albumin infusion were those related to volume overload leading to acute heart failure or pulmonary edema." (PMID 36337861, 2022). "However, as we later show in this study, many children with SM present with low serum albumin concentrations, yet only some of these children develop oedema." (PMID 35398787, 2022). "Proper fluid resuscitation is an important approach for correcting insufficient circulation, but due to the high osmotic pressure of albumin, there may be subsequent fluid overload and pulmonary edema." (PMID 35694666, 2022). "Hossain reported that cerebellar VEGF expression was increased approximately twofold concurrent with the development of cerebellar microvascular hemorrhage, enhanced vascular permeability to serum albumin, and vasogenic cerebellar edema in acute lead intoxication." (PMID 34501321, 2021). "Secondly, low level of albumin could lead to the exudation of intravascular fluid which exacerbate the severity of pulmonary edema." (PMID 32914892, 2020). "Regarding lung injury, both iso-oncotic and hyper-oncotic albumin compared with RL were associated with lower DAD scores (mainly due to decreased edema) and fewer B-lines on lung ultrasonography, which correlates with reduced interstitial edema." (PMID 31311539, 2019). "Pulmonary edema and volume overload following albumin infusion have been reported previously." (PMID 26178624, 2015).
edema (continued). "However, considering the potential side effects of albumin, such as pulmonary edema or fluid overload, it is unclear whether the benefits of albumin infusion outweigh the risks for this population." (PMID 39434907, 2024). "By establishing Catboost model, our study demonstrated that 12 features, including Age, B symptom, Extranodal involvement, ECOG, IPI, Edema/Serous effusion, ALC, AEC, ALB, GLB, LDH, and Chidamide, were significantly related with 2-year OS of AITL patients." (PMID 39263576, 2024). "As it is known that a large burn results in pulmonary complications in patients, we believe that albumin should not be used in this patient group because it may aggravate pulmonary edema, making the patient’s condition more critical." (PMID 36756022, 2023). "Non-cardiogenic pulmonary edema occurs due to increased permeability of microvascular and alveolar compartments with accumulation of highly concentrated plasma proteins (specifically, albumin), as a consequence of hypoxic insult." (PMID 31251771, 2019). "The studies of anti-inflammatory drugs are usually used by nonspecific animal models as follows: the carrageenan, egg albumin or histamine-induced rats paw edema, xylene-induced ear edema in mice, and capillary permeability in mice as well as cotton pellet granuloma in rats." (PMID 30069226, 2018). "However, kwashiorkor in that study was mainly based on serum albumin and some of the children classified as such might not have met today's oedema, WFH, or MUAC criteria for SAM." (PMID 24892281, 2014).
esophageal varices (39 papers, 2011 to 2026). Abnormally dilated veins of the esophagus. "Low serum albumin levels and the presence of esophageal varices have been previously reported as significant risk factors for CHE." (PMID 40142666, 2025). "The ROC curve for the albumin level in predicting esophageal varices showed 2.25 as the cut-off value with 90.3% sensitivity." (PMID 37565128, 2023). "Lower complication rates of esophageal varices, total bilirubin levels, and higher serum levels of albumin and sodium were predictive factors for long-term treatment." (PMID 30563565, 2018). "In addition to serum albumin and zinc levels, the severity of hepatic damage, blood ammonia levels, and esophageal varices have been reported to be useful in predicting CHE." (PMID 40142666, 2025). "Moreover, several other facts have been reinforced in our study which include factors such as low hemoglobin, high Child score, high bilirubin levels, and low albumin lead to higher morbidity and mortality in patients who develop esophageal variceal bleeding." (PMID 38509184, 2024). "Compared to findings from a study by Zein and colleagues, low serum albumin levels in our study had similar sensitivity (52.3%; (95%CI: 41.3–63.0) vs. 52%) and a slightly lower specificity, (49.8%; (95%CI: 40.9–58.3) vs.69%) in predicting esophageal varices." (PMID 31783802, 2019). "Specifically, cohort B showed a higher prevalence of esophageal varices (42.0% vs. 27.6%; p < 0.001), reduced rates of CTP class A (86.0% vs. 91.1%; p = 0.012), and significantly lower serum albumin levels (4.2 vs. 4.3 g/dL; p < 0.001)." (PMID 41511652, 2026). "The patients with esophageal variceal bleeding had lower MELD and CLIF-C-AD scores and better liver synthesis function (measured by protein and albumin), but lower platelet count (90/nL vs. 141/nL, p = 0.001)." (PMID 35625755, 2022). "Most of the studies done to predict the presence of esophageal varices in cirrhotic patients are on either serum ascites albumin gradient or platelet count to splenic diameter as the noninvasive parameter." (PMID 41782982, 2025). "The study findings revealed that the grading of esophageal varices had a strong negative correlation with the platelet count, a moderate negative correlation with albumin and hemoglobin, and a weak negative correlation with INR." (PMID 38916026, 2024).
pancreatitis (39 papers, 2014 to 2026). Inflammation of the pancreas. "Previous studies have indicated that blood urea nitrogen, creatinine, white blood cell count, heart rate, procalcitonin, and albumin can serve as risk factors for patients with pancreatitis." (PMID 41601677, 2026). "Receiver operating characteristic (ROC) curves was used to evaluate the diagnostic performance of CRP/albumin ratio in determining the severity of pancreatitis." (PMID 36268355, 2022). "Pancreatitis is one possible cause of ascites with a low serum ascites albumin gradient." (PMID 37435273, 2023). "Simultaneously, univariate analysis revealed that a decrease in albumin was substantially linked with mortality in this study, implying that serum albumin may possibly have a protective effect in patients with pancreatitis." (PMID 36478954, 2022). "Systemic inflammation and oxidative stress, triggered by pancreatitis, are the primary drivers of impaired liver function and reduced albumin synthesis." (PMID 40403080, 2025). "The correlation between total bilirubin and albumin levels with pancreatitis prognosis underscores the interplay between liver function, nutritional status, and the pathological processes of pancreatitis." (PMID 40403080, 2025). "First, during the acute phase of pancreatitis, ALB production is frequently suppressed as the liver shifts to synthesize acute-phase proteins (e.g., C-reactive protein (CRP)) due to a systemic inflammatory response driven by cytokines (e.g., IL-6)." (PMID 40308642, 2025). "This study aimed to determine the role of aggressive intravenous hydration with lactated Ringer’s solution (LRS) at a specific volume with 20% human albumin before ERCP in reducing the incidence of post-ERCP pancreatitis (PEP)." (PMID 39836543, 2024). "This study aimed to determine the role of aggressive intravenous hydration with lactated Ringer’s solution at a specific volume with 20% human albumin before ERCP in reducing the incidence of post-ERCP pancreatitis." (PMID 39836543, 2024). "Optimum cut-off value of 4.35 was determined for CRP/albumin ratio via highest Youden index at which the sensitivity to predict severe pancreatitis was 87% as compared to 82% for CRP alone." (PMID 36268355, 2022). "CRP/albumin ratio >4.35 had a sensitivity of 87% and accuracy of 76% to predict acute severe pancreatitis." (PMID 36268355, 2022). "Glasgow Pancreatitis score assesses the severity of pancreatitis within 48 hours from admission and includes pointers like age, serum albumin, arterial pO2, serum calcium, blood glucose, serum LDH, serum urea nitrogen (BUN), and WBC count." (PMID 36304788, 2022). "Serum albumin level, total protein level, and lymphocyte counts had dropped at the operation (serum albumin: 2.8 g/dL, total protein: 5.8 g/dL, lymphocyte counts: 1100/μL), and it was thought to be owing to cholangitis and pancreatitis." (PMID 34585307, 2021). "Interestingly, in addition to colon pathology, serum levels of amylase and globulin enzymes were elevated and albumin levels were decreased relative to WT resulting in a reduced albumin/globulin (A/G) ratio known to be associated with chronic inflammatory disease, including pancreatitis." (PMID 30936879, 2019). "Across the included studies, the most frequent predictors were pancreatic duct cannulation, difficult cannulation, pancreatography, female sex, history of pancreatitis, elevated total bilirubin, low albumin, pancreatic duct guidewire use, longer procedure time, and choledocholithiasis." (PMID 40953036, 2025). "Among the 11 tests that consist of APSAVE, we have independently identified several that also have been included in other classification systems: BUN (BISAP and Ranson’s Criteria), creatinine level (APACHE II), serum potassium (APACHE II) and Albumin (Glasgow pancreatitis score)." (PMID 33714951, 2021). "The patients with pancreatitis and trauma were both on critical care and had low albumin levels." (PMID 33425521, 2020).